MYL9 (myosin light chain 9)
Description:
Myosin regulatory subunit that plays an important role in regulation of both smooth muscle and nonmuscle cell contractile activity via its phosphorylation. Implicated in cytokinesis, receptor capping, and cell locomotion. In myoblasts, may regulate PIEZO1-dependent cortical actomyosin assembly involved in myotube formation (By similarity).
Synonyms: LC20; MLC2; MRLC1; MYRL2; MLC-2C; MMIHS4
Tractability: PROTAC: ubiquitination databases record sites on it.
Gene: Protein-coding gene on chromosome 20 (36,541,490 to 36,551,447, forward strand). Ensembl gene ENSG00000101335.
Subcellular location: Cytoplasm, cytoskeleton; Cytoplasm, cell cortex
Pathways (Reactome):
Signal Transduction: RHO GTPases Activate ROCKs; RHO GTPases activate CIT; RHO GTPases activate PAKs; RHO GTPases activate PKNs
Developmental Biology: EPHA-mediated growth cone collapse; Sema4D induced cell migration and growth-cone collapse
Gene expression (Transcription): RUNX1 regulates genes involved in megakaryocyte differentiation and platelet function
Muscle contraction: Smooth Muscle Contraction
Gene Ontology:
Molecular function: structural constituent of cytoskeleton; myosin heavy chain binding; structural constituent of muscle; calcium ion binding
Biological process: platelet aggregation; stress fiber assembly; myofibril assembly; regulation of muscle contraction; vascular associated smooth muscle contraction
Cellular component: stress fiber; cytoplasm; cytoskeleton; cytosol; muscle myosin complex; myofibril; myosin II complex; cell cortex; Z disc
Genetic constraint (gnomAD): Loss-of-function variants: 7 observed, 13.62 expected, observed/expected ratio (o/e) 0.51, 90% interval 0.29 to 0.97. The upper end of that interval is the gene's LOEUF score, 0.97, which puts it in group 4 of 6, group 1 being the genes least tolerant of losing a copy. Missense variants: 190 observed, 255.13 expected, observed/expected ratio (o/e) 0.74, 90% interval 0.66 to 0.84. Synonymous variants: 81 observed, 91.42 expected, observed/expected ratio (o/e) 0.89, 90% interval 0.74 to 1.07.
Homologues: Orthologues: chimpanzee MYL9 (100% identical), dog MYL9 (100% identical), guinea pig MYL9 (100% identical), macaque MYL9 (100% identical), rabbit MYL9 (100% identical), mouse Myl9 (99% identical), rat Myl9 (99% identical), pig MYL9 (98% identical), tropical clawed frog myl9 (97% identical), zebrafish myl9b (95% identical), zebrafish myl9a (93% identical), Drosophila melanogaster sqh (81% identical), and 1 more. Paralogues in human: MYL12A (93% identical), MYL12B (93% identical), MYL10 (56% identical), MYL11 (55% identical), MYL2 (55% identical), MYL5 (54% identical), MYL7 (48% identical).
Diseases named in the same sentence as MYL9 in open-access papers:
MYL9 is named in the same sentence as 104 diseases in open-access papers, as found by Europe PMC text mining. Sharing a sentence is not in itself a finding about the gene and the disease. The quoted sentences say what the papers report.
colorectal cancer (18 papers, 2020 to 2026). A primary or metastatic malignant neoplasm that affects the colon or rectum. "In the current study, MYL9, a pivotal gene associated with recurrence in colorectal cancer patients, was selected to determine its role in colorectal cancer." (PMID 34974798, 2022). "MYL9 is also associated with the recurrence of colorectal cancer." (PMID 35768705, 2022). "MYL9 is critically associated with actin stress fiber assembly and actomyosin contractility, and plays a crucial role in a variety of malignant tumors, such as breast cancer, colorectal cancer, bladder cancer, and NSCLC." (PMID 36273228, 2022). "MYL9 plays a key role in early-onset colorectal cancer (CRC) by influencing the cGMP-PKG and oxytocin signaling pathways." (PMID 39768172, 2024). "The targets of MRTF are more prevalent with the increase in cancer progression from normal fibroblast cells to CAFs, and MYL9 expression is increased in CAFs in colorectal cancers." (PMID 39768172, 2024). "Increased expression of myosin light chain 9 (MYL9) has been reported in early-stage and recurrent colorectal cancer tissues." (PMID 34974798, 2022). "Mechanically, MYL9 promoted the proliferation, invasion, migration and angiogenesis of colorectal cancer cells via YAP1-Hippo signaling." (PMID 34974798, 2022). "BGN and MYL9 were also found to be fibroblast-specific markers of poor prognosis in colorectal cancer." (PMID 36589754, 2022). "The increased expression of MYL9 in early-stage colorectal cancer tissues and recurrent colorectal cancer tissues has been mentioned previously." (PMID 34974798, 2022). "The authors highlighted that the overexpressed BGN, RCN3, TAGLN, MYL9 and TPM2 in cancer-associated fibroblast as potential prognostic biomarkers for patients with colorectal cancers." (PMID 36172359, 2022). "A recent report performed in several colorectal cancer cell lines also showed that MYL9 overexpression promoted cell proliferation, invasion, migration and angiogenesis." (PMID 36273228, 2022). "Subsequently, YAP1 silencing or Hippo antagonist was performed to clarify the regulatory mechanisms of MYL9 in colorectal cancer progression." (PMID 34974798, 2022). "The results from Prognoscan and Kaplan–Meier plotter databases showed that MYL9 expression correlated significantly with prognosis in lung cancer, breast cancer, colorectal cancer, brain glioma, prostate cancer, especially ovarian cancer and gastric cancer." (PMID 34729929, 2022). "MYL9 expression in several colorectal cancer cell lines was detected by Western blotting and RT-qPCR." (PMID 34974798, 2022). "We found that in the Prognoscan data set, multiple cancers showed a marked correlation between the prognosis of patients and the expression level of MYL9 including lung, ovarian, blood, prostate, brain, breast, and colorectal cancer." (PMID 34729929, 2022). "In conclusion, this study elucidated that MYL9 potentially regulated cell proliferation, migration, invasion and angiogenesis in colorectal cancer by interacting with YAP1 and regulating Hippo signaling." (PMID 34974798, 2022). "In this study, it was found that MYL9 expression was notably elevated in several human colorectal cancer cell lines." (PMID 34974798, 2022). "Overall, MYL9 promotes the proliferation, invasion, migration and angiogenesis of colorectal cancer cells by binding to YAP1 and thereby activating Hippo signaling." (PMID 34974798, 2022). "MYL9 protein and mRNA expression was upregulated in colorectal cancer cell lines SW480, SW620, HT-29 and HCT116, compared with the NCM460 cells." (PMID 34974798, 2022). "In general, these results demonstrate that MYL9 promotes the proliferation, migration and invasion of colorectal cancer cells through YAP1-Hippo signaling." (PMID 34974798, 2022). "We suggest that expression of MYL9 is positively correlated with the angiogenic ability of colorectal cancer cells." (PMID 34974798, 2022).
colorectal cancer (continued). "In our experiments, MYL9 was found to promote proliferation, invasion, migration, angiogenesis in colorectal cancer cells via binding to YAP1 and regulating Hippo signaling." (PMID 34974798, 2022). "Compelling evidence indicates that MYL9 protein expression increases significantly with tumor recurrence and MYL9 level is elevated in early-stage and recurrent colorectal cancer tissues." (PMID 34974798, 2022). "Furthermore, our analysis showed that high expression of MMP11 and MYL9 in human colorectal cancer was inversely correlated with TMB." (PMID 41009818, 2025). "This work on MYL9 identified its novel effects in colorectal cancer." (PMID 34974798, 2022). "MYL9 is one of the fibroblast-specific biomarkers of poor prognosis in colorectal cancer." (PMID 34974798, 2022). "This study confirmed that MYL9 was highly expressed several colorectal cancer cell lines and MYL9 silencing inhibited cell proliferation, invasion, migration and angiogenesis, while MYL9 overexpression promoted cell proliferation, invasion, migration and angiogenesis." (PMID 34974798, 2022). "Additionally, it has been suggested that MYL9 expression is increased in early-stage and recurrent colorectal cancer tissues." (PMID 34974798, 2022). "This study aimed to investigate the precise role of MYL9 on the progression of colorectal cancer." (PMID 34974798, 2022). "Then, MYL9 was silenced or overexpressed to explore whether MYL9 affects the biological behavior of colorectal cancer cells." (PMID 34974798, 2022). "In the current study, the expression of MYL9 in several colorectal cancer cell lines was detected." (PMID 34974798, 2022). "Experimental results showed that MYL9 expression was elevated in colorectal cancer cell lines." (PMID 34974798, 2022). "The TAGLN, MYL9, and TPM2 were found to be over-expressed in fibroblasts from primary tumors compared to adjacent normal tissues and were associated with a poorer prognosis in the TCGA cohort of colorectal cancer." (PMID 34771544, 2021). "Results of the current study indicated that MYL9 knockdown attenuated the tubule formation capacity of HCT116 cells, suggesting the potential pro-angiogenic role of MYL9 in colorectal cancer." (PMID 34974798, 2022). "BGN, RCN3, TAGLN, MYL9, and TPM2 were identified as fibroblast-specific biomarkers with a poor prognosis in colorectal cancer." (PMID 35785171, 2022). "The present study revealed that MYL9 deletion downregulated the expression of MMP2 and MMP9 while MYL9 overexpression upregulated the expression of MMP2 and MMP9 in colorectal cancer cells." (PMID 34974798, 2022). "Based on the BioGRID database, it was demonstrated that MYL9 could bind to YAP1, which is a pro-cancer signaling pathway involved in colorectal cancer." (PMID 34974798, 2022). "However, the specific role and regulatory mechanisms of MYL9 in colorectal cancer have not been extensively investigated." (PMID 34974798, 2022).
breast carcinoma (15 papers, 2017 to 2025). "Furthermore, MYL9 expression was distinctively associated with prognosis in adrenocortical carcinoma, colon adenocarcinoma, brain glioma, lung cancer, ovarian cancer, gastric cancer, breast cancer, blood cancer, and prostate cancer patients." (PMID 34729929, 2022). "Kaplan–Meier plots revealed that cancer with lower or decreased expression of MYL9 showed better overall survival (OS) and better post-progression survival in gastric, ovarian, and breast cancer." (PMID 39768172, 2024). "MYL9 expression promotes invasion in breast cancer cell lines and a hypermotile phenotype, and it is localized to the invasion edge of tumor cells, suggesting that MYL9 is indeed involved in invasion-promoting factors in several cancers." (PMID 39768172, 2024). "Overexpression of myocardin-related transcription factor A significantly promotes the migration of breast cancer cells through reverse transcription of MYL9 and CYR61 genes." (PMID 34974798, 2022). "In breast cancer, MYL9 is activated by myocardin-related transcription factor-A and promotes MCF-7 cell migration." (PMID 36589754, 2022). "Studies have detected the expression of MYL9 in various tumors, revealing that it was upregulated in breast cancer as well as liver cancer, while downregulated in prostate cancer and bladder cancer 41-44, however, it is controversial in CRC." (PMID 32127961, 2020). "Toward understanding the mechanisms of breast cancer progression, we have previously reported that STAT3 promotes breast cancer cell migration by regulating Cyr61 and Myl9 expression." (PMID 31409371, 2019). "The high expression of MYL9 in breast cancer, esophageal squamous cell carcinoma, liver cancer, and epithelial ovarian cancer is associated with poor prognosis, while the low expression of MYL9 in non-small cell lung cancer, bladder cancer, and prostate cancer is associated with poor prognosis." (PMID 37926835, 2023). "Furthermore, we integrated the information on MYL9-binding components and MYL9 expression-related genes in breast cancer for a series of enrichment analyses." (PMID 36846347, 2023). "MYL9 was lowly expressed in most cancers, such as breast cancer, lung adenocarcinoma and squamous cell carcinoma, and stomach adenocarcinoma; but it was highly expressed in several cancers, such as cholangiocarcinoma, head and neck squamous cell carcinoma, and liver hepatocellular carcinoma." (PMID 34729929, 2022). "In the myeloid compartment, metastatic breast cancer patients show enrichments of inflammatory monocytes characterised by high RORA, MYL9 and ITGB5 transcription." (PMID 40340807, 2025). "In breast cancer (BC) cells, SMYD3 can regulate the cell cycle and promote cancer cell migration by combining with the cyclin A1 (CCNA1) and myosin light chain 9 (MYL9) promoters." (PMID 34335697, 2021). "Studies exhibited that MYL9 was involved in regulating breast cancer invasion, and MYL9 depletion did not influence cell cycle progression or induce cell death in MDA‐MB‐231 cells but obviously reduced invasiveness." (PMID 34729929, 2022). "In vivo mouse experiments found that siRNA knockdown of Myl9 expression reduces invasion and lung colonization of two highly metastatic tumor cell lines, human MDA‐MB‐231 breast carcinoma and mouse B16F2 melanoma, suggesting an important role for Myl9's cytoskeletal functions in metastasis." (PMID 33031641, 2020). "Moreover, RAC1, CDC42, MYL9, MYLK, ABL1, and other genes have been proved to be related to the progress of human breast cancer." (PMID 33306680, 2020).
colon carcinoma (14 papers, 2013 to 2023). "Low MYL9 expression has been associated with poor survival among patients with colon cancer." (PMID 34821071, 2022). "The GEPIA database was used to analyze MYL9 mRNA expression levels in colon cancer, rectal cancer, and normal tissues." (PMID 37926835, 2023). "MYL9 interacts with the transcriptional regulator YAP1 in colon carcinoma cells and alters the expression of YAP1-regulated genes." (PMID 35802750, 2022). "Total expression of MYL9 has been shown to be downregulated in tumor tissues, compared with normal tissues, in colon cancer, noninvasive small‐cell lung cancer, and bladder cancer." (PMID 34821071, 2022). "For example, it has been shown that MYL9 mediates the proliferation, migration and invasion of colon cancer tumor stem cells by interacting with sponge microRNA-412-3p and long-stranded non-coding RNA MBNL1-AS1." (PMID 34974798, 2022). "For example, in colon cancer, MYL9 expression was downregulated in tumor tissues compared with normal tissues and the area under the curve (AUC) of MYL9 in diagnosis for colon cancer was 0.826, indicating statistical significance." (PMID 34729929, 2022). "Compared to adjacent normal colon, upregulation of Defa6 and Bcl3 and downregulation of App, Myh11, and Myl9 indicated changes in tight junctions and anti-microbial activity in Pirc colon tumors." (PMID 34494932, 2021). "Emerging evidence supports that MBNL1-AS1 plays an inhibitory role in colon cancer by upregulating miR-412-3p-targeted MYL9." (PMID 33648424, 2021). "Clinical evidence indicates that MYL9 expression is decreased in patients with bladder cancer, colon cancer, non–small cell lung cancer, and prostate cancer." (PMID 28388691, 2017). "Interestingly, multiple genes involved in calcium signaling (FBN1, CALD1, MGP and MYL9) were co-overexpressed with TAZ-AXL-CTGF in colon cancer." (PMID 23372686, 2013). "The similar mechanism occurs in colon cancer; the study revealed an inhibitory role of MBNL1-AS1 by upregulating miR-412-3p-targeted MYL9." (PMID 35518784, 2022). "As an example, IG-SVM achieved a classification accuracy of 90.32% for colon cancer, which is difficult to be accurately classified, only based on three genes including CSRP1, MYL9, and GUCA2B." (PMID 29246519, 2017). "Four genes that are involved in calcium binding or signaling were co-regulated with TAZ-AXL-CTGF in the colon cancer specimens, including FBN1, CALD1, MGP and MYL9." (PMID 23372686, 2013). "The significant expression of Myl9/12 protein was detected in the colon from UC patients, whereas the normal non-inflamed colonic mucosa obtained from colon cancer patients showed the limited expression of Myl9/12 protein." (PMID 33584659, 2020).
prostate carcinoma (9 papers, 2016 to 2023). A carcinoma that arises from epithelial cells of the prostate gland. "MYL9 downregulation is associated with unfavorable prognosis in patients with colon and prostate cancer, which is opposite to our result Studies have shown the functional role of myosin II may differ from cancer to cancer." (PMID 28388691, 2017). "Low MYL9 expression correlated with poor survival in colon and prostate cancer, suggesting that MYL9 is a favorable prognostic marker." (PMID 28388691, 2017). "The myosin light chain (MYL9) in stroma has been shown to predict malignant progression and recurrence-free survival in prostate cancer." (PMID 27124473, 2016). "Moreover, it had been reported that MYL9 may efficiently predict recurrence-free survivals in prostate cancer patients." (PMID 27634882, 2016).
esophageal squamous cell carcinoma (6 papers, 2017 to 2024). Esophageal squamous cell carcinoma (ESCC) is a type of esophageal carcinoma (EC) that can affect any part of the esophagus, but is usually located in the upper or middle third. "Over-expression of MYL9 in tumor cells was associated with poorer OS and recurrence-free survival in esophageal squamous cell carcinoma." (PMID 34771544, 2021). "Previous studies have shown that high expression of MYL9 is associated with poorer prognosis in patients with early-onset CRC, epithelial ovarian cancer, esophageal squamous cell carcinoma and glioma." (PMID 36910014, 2023). "Aberrant Expression of MYL9 is correlated with prognosis of glioblastoma and esophageal squamous cell cancer, and it may act as a novel biomarker." (PMID 37768204, 2023). "Myosin light chain 9 (MYL9) is necessary for cytoskeletal dynamics and experimental metastasis, but its expression in esophageal squamous cell carcinoma (ESCC) has not been addressed." (PMID 28388691, 2017).
asthma (5 papers, 2018 to 2025). "CD69 binding to Gal-1 on DCs induces IL-10+ T cells with anti-inflammatory properties, while its interaction with Myl9/12 recruits activated T cells to inflamed lungs in asthma." (PMID 40574085, 2025). "Conversely, Myl9/12 contributes to the development of pathogenetic inflammation, such as that in asthma, ECRS, and bowel disease." (PMID 38540778, 2024). "Compared with the control group, the expression of Fos, Myl9 and Tlr4 in the asthma model was increased, while the expression of Smg7, Sumo2 and Stat5a was decreased." (PMID 36726128, 2023). "Additionally, based on the previously published literatures on asthma and inflammation, we screened out down-regulated genes, such as Smg7, Sumo2, and Stat5a, and up-regulated genes, such as Myl9, Fos and Tlr4." (PMID 36726128, 2023). "We also found that lncRNA NONMMUT052633 had positive correlation with Myl9, which may be considered as a promising target for the treatment of asthma." (PMID 36726128, 2023). "This study confirmed the expression of peptides corresponding to ACTA2, ACTB, ACTG1, MYH11, FLNA, MYL9, and TAGLN in both control guinea pigs and the asthma model." (PMID 40980809, 2025). "Based on immunohistochemistry data, the interactomes related to the expression of MYH11, MYL9, ACTG1, ACTA2, ACTB, TAGLN, and FLNA in the bronchial smooth muscle of guinea pigs in an asthma model were generated." (PMID 40980809, 2025). "MYH11, MYL9, ACTA2, and TAGLN are involved in various pathologies, including the excessive contraction observed in ASM in asthma." (PMID 40980809, 2025). "In asthma model guinea pigs, ACTG1 expression significantly decreased compared to controls, while the expression levels of ACTB, ACTA2, and MYL9 significantly increased (p < 0.01, n = 5, each group)." (PMID 40980809, 2025). "MYL9, which is essential for the activation of myosin ATPase and actomyosin interaction, exhibited increased expression in the ASM of guinea pigs with an asthma model." (PMID 40980809, 2025).